CDC5L (cell division cycle 5 like)
Diseases named in the same sentence as CDC5L in open-access papers (continued):
Sharing a sentence is not in itself a finding about the gene and the disease.
ovarian carcinoma (2 papers, 2020 to 2025). A malignant neoplasm originating from the surface ovarian epithelium. "We further showed that CDC5L promoted PEAK1 expression in ovarian cancer cells, indicating that CDC5L can act as a transcription factor to activate PEAK1 expression." (PMID 32167655, 2020). "After CDC5L overexpression, the proliferation rate of ovarian cancer cells and the number of migrating and invading cells both significantly increased, whereas the apoptosis rate of the cells significantly decreased." (PMID 32167655, 2020). "CDC5L was a direct target of miR‐542‐3p and played an oncogenic role in ovarian cancer cells." (PMID 32167655, 2020). "Further detection of PEAK1 protein expression in CDC5L‐overexpressing and ‐silenced ovarian cancer cell lines showed that PEAK1 protein expression level significantly increased after CDC5L overexpression, whereas PEAK1 protein expression level significantly decreased after CDC5L silencing." (PMID 32167655, 2020). "Next, we further studied whether CDC5L was involved in circ‐PGAM1‐mediated regulation of ovarian cancer cells." (PMID 32167655, 2020). "The circ‐PGAM1/miR‐542‐3p/CDC5L/PEAK1 pathway played an important role in the progression of ovarian cancer and might be a novel therapeutic target for ovarian cancer." (PMID 32167655, 2020). "Furthermore, the circ‐PGAM1/miR‐542‐3p/CDC5L/PEAK1 axis might be a potential therapeutic target in ovarian cancer." (PMID 32167655, 2020). "This study also confirmed that CDC5L expression was high in EOC tissues, promoted proliferation, migration, and invasion of ovarian cancer cells, and inhibited the apoptosis of ovarian cancer cells." (PMID 32167655, 2020). "By increasing miR‐542‐3p expression, circ‐PGAM1 silencing increased its inhibitory effect on CDC5L to decrease CDC5L expression.CDC5L expression was upregulated in EOC tissues, and CDC5L overexpression promoted the malignant biological behaviors of ovarian cancer cells." (PMID 32167655, 2020). "Our results showed that CDC5L (without 3′‐UTR) overexpression reversed the inhibition of malignant behaviors of ovarian cancer cells by miR‐542‐3p and increased the expression levels of PEAK1, p‐ERK1/2, and p‐JAK2." (PMID 32167655, 2020). "Since PEAK1 was activated by CDC5L and miR‐542‐3p regulated the malignant biological behaviors of ovarian cancer cells through targeting the CDC5L 3′UTR, we next examined whether PEAK1 and downstream pathways were involved in the tumor‐suppression effect of miR‐542‐3p on ovarian cancer cells." (PMID 32167655, 2020).
breast tumors (1 paper, 2023). "BCAS2 was first identified as a highly expressed oncogenic gene in breast tumors, and was later found to be the core component of CDC5L/Prp19 splicing complex, which mainly takes part in pre-mRNA splicing and DNA damage response." (PMID 37901468, 2023).
chronic obstructive pulmonary disease (1 paper, 2021). A chronic and progressive lung disorder characterized by the loss of elasticity of the bronchial tree and the air sacs, destruction of the air sacs wall, thickening of the bronchial wall, and mucous accumulation in the bronchial tree. "Previous studies identified CDC5L as a bridge gene linking lung adenocarcinoma and chronic obstructive pulmonary disease." (PMID 34573320, 2021).
diabetes (1 paper, 2020). "The expression of CDC5L was not related to age, gender, smoking status, BMI, diabetes status, or T stage but significantly correlated with histologic grade, N stage and M stage." (PMID 31897231, 2020).
kidney damage (1 paper, 2021). "The other six markers, CDC5L, HNRNPU, NUDT21, PAPOLA, POLR2B, and WBP4, were all negatively correlated with GFR, indicating that these genes may aggravate kidney damage in patients with LN." (PMID 34557492, 2021).
Leigh disease (1 paper, 2012). "A multitherapeutic strategy involving both targeting respiratory chain complex I and CDC5L formations could thus be envisaged for a more comprehensive targeting of the factors associated to Leigh disease." (PMID 22279562, 2012). "A large number of drugs are associated to this complex, however the association between CDC5L and Leigh disease has not been mentioned so far." (PMID 22279562, 2012).
Myocardial fibrosis (1 paper, 2025). "Finally, RT-PCR analysis revealed that the transcript levels ofcol1a1 andcol3a1, which are markers of myocardial fibrosis, were significantly decreased in the CDC5L-overexpressing group; however, this anti-fibrotic effect of CDC5L was largely reversed followingFGF10 knockdown." (PMID 41239804, 2025).
myocardial infarction (1 paper, 2025). Gross necrosis of the myocardium, as a result of interruption of the blood supply to the area, as in coronary thrombosis. "The present study confirmed that CDC5L promotes cardiomyocyte proliferation and inhibits apoptosis in the peri-infarct zone after myocardial infarction." (PMID 41239804, 2025).
neuroblastoma (1 paper, 2021). Neuroblastoma (NB) is the most common solid, extracranial childhood tumor. "Cdc5L could be a potential molecular marker in neuroblastoma and may play an important role in mitosis and cell activity during female flower bud formation." (PMID 33888140, 2021).
schizophrenia (1 paper, 2016). A major psychotic disorder characterized by abnormalities in the perception or expression of reality. "DISC1 network of PPIs involved CDC5L indicates the protein or complexes that have been linked to schizophrenia." (PMID 28117656, 2016). "It implicates that the DISC-1 associated CDC5L complex may explain the epigenetic mechanism in stress-induced prefrontal dysfunction in schizophrenia." (PMID 28117656, 2016).
urothelial carcinoma (1 paper, 2025). A malignant neoplasm derived from the transitional epithelium of the urinary tract (urinary bladder, ureter, urethra, or renal pelvis). "Of the proteins shared by networks A and C, the 2 PPI networks specific to papillary urothelial carcinoma, CDC5L and CUL1, have been found to be upregulated in urothelial carcinoma in previous studies." (PMID 41342186, 2025).
cancer (27 papers, 2004 to 2025). A tumor composed of atypical neoplastic, often pleomorphic cells that invade other tissues. "Previous studies have shown that CDC5L promotes cancer cell proliferation, inhibits cancer cell apoptosis, and promotes cancer progression." (PMID 41239804, 2025). "GO and KEGG enrichment analyses revealed the close relationship of FUBP1 with RNA splicing and the Cdc5L (cell division cycle 5-like protein) complex in all cancer types." (PMID 35274005, 2022). "Among the differentially expressed genes in primary samples, 7 of 39 genes (VHL, GNE, POLH, MAPK13, NOP14, INADL, CDC5L) were reported to be cancer-related in the literature." (PMID 28009993, 2017). "The deletion of endogenous Cdc5L decreases cell viability via dramatic mitotic arrest, which has not been reported in plants, but has been widely studied in animals, especially in the proliferation of cancer cells." (PMID 33888140, 2021). "Previous studies have revealed that CDC5L plays an active role in the development of cancers." (PMID 31897231, 2020). "Of these genes, CDC5L may be an important gene in cancer because of its role as a positive cell cycle regulator for G2/M transition." (PMID 15298715, 2004). "TFs associated with PIK3CA mutations were involved in WNT signaling, epithelial–mesenchymal transition, and cancer stem cell transition, including ELF3, TFEC, STAT4, STAT5B, NFATC1, GLIS1, CDC5L and AR." (PMID 36243974, 2022). "Other genes, such as ALOXE3, HBQ1, KREMEN2, SYT13, DOK7, CDC5L, and FBXO6, have been reported in several cancers." (PMID 28404969, 2017). "Therefore, BTYNB can be used as a reagent to target multiple pathways (C-Myc, CDC5L, EZH2, etc.)or be used in combinatorial targeting strategies to modulate the cell cycle and enhance apoptosis of cancer cells more effectively." (PMID 39534570, 2024). "The authors showed, using the Cancer Cell Line Encyclopedia (CCLE) that GLO1 mRNA expression positively correlated with the expression of spliceosome proteins (PPIL1 and CDC5L), suggesting increased GLO1 expression protects spliceosome proteins in tumour cells." (PMID 35409048, 2022).
tumor (17 papers, 2010 to 2025). "The interaction of CDC5L with module-5 proteins which were functionally associated with enzyme activity, neoplasm, and nervous system diseases." (PMID 34918006, 2022). "Analysis of baseline data from these 80 patients showed a positive correlation between CDC5L expression and larger tumor size, as well as advanced T and N stages." (PMID 39990666, 2025). "A positive correlation between Prp19 and CDC5L in tumor tissues was also confirmed, and similar results were observed in Western blot analyses." (PMID 39990666, 2025). "CDC5L's involvement in various malignant tumor behaviors prompted our investigation into its role in GC progression." (PMID 39990666, 2025). "Our study reveals that CDC5L is upregulated in GC, promoting tumor proliferation, migration, invasion, and oxaliplatin resistance." (PMID 39990666, 2025). "In 80 GC patients from our center, both mRNA and protein levels of CDC5L were significantly higher in tumor tissues compared to normal tissues, a finding echoed by TCGA data." (PMID 39990666, 2025). "The role of DDX21 and CDC5L on the cell proliferation, cell cycle and tumor growth were evaluated both in vitro and in vivo." (PMID 34903139, 2021). "It was observed that knockdown of CDC5L significantly reduced the tumour cell migration and invasion abilities compared to the control group." (PMID 31897231, 2020). "And CDC5L has a positive effect on the tumour cell migration and invasion abilities by cell scratch assay and Transwell assay." (PMID 31897231, 2020). "Consistently, the sh-CDC5L group showed slower growth of the tumour xenografts compared with the sh-NC group." (PMID 31897231, 2020). "After 5 weeks of tumour implantation, the tumour xenograft sizes of the sh-CDC5L group were dramatically reduced compared with the sh-NC group." (PMID 31897231, 2020). "Immunohistochemistry (IHC) results also demonstrated elevated CDC5L expression in tumor tissues." (PMID 39990666, 2025). "Overall, EIF4A3 and CDC5L are expected to become tumor biomarkers." (PMID 40092703, 2025). "We found that all tumor cells share the vast majority of these mutations (i.e., they are clonal), including variants affecting genes previously associated with CRC progression (e.g., INPP1, CDC5L, ROR2, EXOSC5)." (PMID 35081992, 2022). "MiR‐542‐3p played a tumor‐suppressing role through downregulation of CDC5L." (PMID 32167655, 2020). "Furthermore, DDX21 interacted with CDC5L to exert the tumor-promoting effects in CRC." (PMID 34903139, 2021). "Xenograft model revealed that knockdown of CDC5L and PARP inhibitors had a synergistic effect in inhibiting tumor growth." (PMID 39990666, 2025). "Cell division cycle 5-like protein (CDC5L) is essential for mitotic progression, and its target gene, AGRN, seems to be modulated by NEAT1, yielding this whole pathway critical for tumor growth." (PMID 33917553, 2021). "Studies have found that CDC5L was highly expressed in HCC tissues and was significantly related to AJCC stage, tumor size, and Ki-67." (PMID 32955083, 2020). "In addition, CDC5L bound to the ARGN promoter to promote ARGN expression and formed a NEAT1‐CDC5L‐ARGN‐positive feedback loop to synergistically exert tumor‐promotion functions." (PMID 32167655, 2020). "Therefore, it was hypothesized that CDC5L might bind to the PEAK1 promoter to regulate PEAK1 expression and further activate downstream signaling pathways to synergistically play a tumor‐promoting role." (PMID 32167655, 2020). "Tumor cells lacking CDC5L may suffer from mitotic arrest and DNA damage." (PMID 39534570, 2024).
infection (4 papers, 2020 to 2025). The state of being infected such as from the introduction of a foreign agent such as serum, vaccine, antigenic substance or organism. "The CCK-8 proliferation assay indicated that the proliferation of T24 and UMUC3 cells was suppressed markedly following infection with si-CDC5L." (PMID 31897231, 2020). "In contrast, RNAs related to checkpoint signaling (e.g., CDK5RAP3 and CDC5L) and meiotic cell cycle (e.g., TOP2A) were decreased in the cells infected by Salmonella compared to cells without infection under the aerobic condition." (PMID 37040488, 2023).
CDC5L also shares sentences with these, for which no sentence is quoted: cervical tumors (4 papers); atrial fibrillation (2); colorectal tumor (2); dementia (2); gastric cancer (2); Stroke (2); Bell's palsy (1); bladder tumour (1); cardiovascular diseases (1); COVID-19 (1); diabetic nephropathy (1); dilated cardiomyopathy (1); epilepsy (1); intestinal cancer (1); liver cancer (1); lung adenocarcinoma (1); lung fibrosis (1); mismatch repair deficiency (1); nervous system diseases (1); non-small cell lung carcinoma (1); Parkinson’s (1); psoriasis (1); renal cell carcinoma (1); serous ovarian cancer (1); staphylococcus aureus infection (1).